OSMR (oncostatin M receptor)
Diseases named in the same sentence as OSMR in open-access papers (continued):
Sharing a sentence is not in itself a finding about the gene and the disease.
chronic rhinosinusitis (1 paper, 2023). Chronic form of sinusitis. "The elevated mRNA levels of OSM and OSMRβ in conjunction with these specific cytokines underscore the multifaceted nature of chronic rhinosinusitis, implicating OSM as a potential key player in the regulation of inflammatory processes." (PMID 38137445, 2023).
congestive heart failure (1 paper, 2023). Failure of the heart to pump a sufficient amount of blood to meet the needs of the body tissues, resulting in tissue congestion and edema. "The ratios of lung weight to body weight were greater in OSMR-KO mice than in WT mice 4 weeks after AB surgery, suggesting the exacerbation of pulmonary oedema and congestive heart failure development in OSMR-KO mice subjected to AB." (PMID 37120549, 2023).
depressive episodes (1 paper, 2025). "ICAM1 and OSMR have been linked to depressive episodes in a recent study." (PMID 39911945, 2025).
diabetes (1 paper, 2017). "Using immune-cytochemistry with an antibody directed against OSMR, we would suggest to investigate whether the up-regulation of OSMR observed in our diabetes models for lysates taken from the whole retina, is localized to the RPE layer within the retina." (PMID 28575111, 2017).
diffuse systemic sclerosis (1 paper, 2020). "OSMRβ was recently identified as a prognostic biomarker that correlates with progression of the skin disease in patients with diffuse systemic sclerosis (dcSSc)." (PMID 32736577, 2020).
enterocolitis (1 paper, 2021). An inflammatory process affecting the small intestine and colon. "In this work, we report on a Whole-Exome Sequencing (WES) performed on 12 HAEC patients and 12 HSCR patients without enterocolitis that allowed us to identify OSMR as a HAEC candidate gene, further investigated by proteomics." (PMID 33917126, 2021). "Here we report on Whole-Exome Sequencing (WES) performed on 12 HSCR patients without enterocolitis and 12 patients with HAEC that allowed us to identify an HAEC predisposing variant located in the Oncostatin-M receptor (OSMR) gene, further investigated by proteomic analysis." (PMID 33917126, 2021).
infarction (1 paper, 2023). A localised pathological necrosis of tissue resulting from obstruction of the blood supply usually by a thrombus, an embolus, or vascular torsion. "Previous studies demonstrated that therapeutic application of recombinant mOSM markedly improved cardiac performance and dramatically increased survival after infarction, whereas strains with OSMR deletion showed a reduced ejection fraction and high mortality." (PMID 37120549, 2023).
ischemic heart disease (1 paper, 2021). "Loss- and gain-of-function studies in animal models of ischemic heart disease revealed a crucial role of OSMR and LIFR activation for cardiac repair." (PMID 35008777, 2021).
kidney stone (1 paper, 2020). "In the kidneys of OSMRβ−/− mice, there was considerably less formation of GOx-induced crystal deposits than in WT mice on day 6, suggesting that OSM signaling may promote the formation of renal crystal deposits in the process of kidney stone formation." (PMID 33051515, 2020).
lymphoma (1 paper, 2023). A malignant (clonal) proliferation of B- lymphocytes or T- lymphocytes which involves the lymph nodes, bone marrow and/or extranodal sites. "Among the novel N3a-sensitive PI3K/mTOR-reducing proteins in lymphomas, were increased PHLDA3 (R_cHL/MCL), OSMR (R_cHL), COL6A3, and Rictor (P_ALCL/cHL)." (PMID 37568720, 2023).
mucinous carcinomas (1 paper, 2018). "There are six genes (MAL, MYOD1, OSMR, SEPTIN9, SFRP1, and SFRP4) for which hypermethylation is observed almost exclusively or preferentially in mucinous carcinomas." (PMID 29882921, 2018).
Myocardial fibrosis (1 paper, 2023). "At the tissue level, picrosirius red (PSR) staining of transverse heart sections confirmed that myocardial fibrosis was exacerbated in the hearts of OSMR knockout mice compared with WT controls." (PMID 37120549, 2023).
perinatal disease (1 paper, 2024). A condition affecting an unborn or newly born individual, where the perinatal period is defined in humans as commencing at 22 completed weeks (154 days) of gestation and ending seven completed days after birth. "OSM/OSMR signaling plays an important role in inflammation, hematopoiesis, development, and is increasingly recognized as an important factor in cancer progression, but is still underrepresented in perinatal disease studies." (PMID 39148025, 2024).
periodontitis (1 paper, 2024). An acute or chronic inflammatory process that affects the tissues that surround and support the teeth. "Periodontitis-induced bone loss was inhibited in osteogenic cell-specific OSMR-deficient mice, demonstrating the in vivo relevance of OSM-mediated neutrophil–osteogenic cell crosstalk." (PMID 38413562, 2024). "Taken together, our findings indicate that neutrophils contribute to bone destruction in periodontitis by activating the OSMR/RL-D4/RANKL axis in osteogenic cells." (PMID 38413562, 2024). "To investigate the importance of OSMR signaling in osteogenic cells in periodontitis-induced bone damage in vivo, we crossed OSMR-floxed mice with Sp7-Cre mice." (PMID 38413562, 2024). "In this study, we demonstrated that the neutrophil–osteogenic cell interaction promotes bone destruction in periodontitis through oncostatin M (OSM)/OSM receptor (OSMR) signaling." (PMID 38413562, 2024).
plaque psoriasis (1 paper, 2020). "Although the findings obtained have not yet been reported, the efficacy of KPL-716, a monoclonal antibody against OSMRβ (oncostatin M receptor β, a subunit for IL-31 receptor), was evaluated in a pilot phase II study on patients with disease-accompanying itch, including those with plaque psoriasis." (PMID 33182442, 2020).
preeclampsia (1 paper, 2024). Preeclampsia is a hypertensive disorder of pregnancy that is characterized by new-onset hypertension with proteinuria presenting after 20 weeks of gestation, and depending on mild or severe forms may initially present with severe headache, visual disturbances, and hyperreflexia. "This study, through the analysis of a placental dataset, identified inflammation-related genes such as CXCR6, PIK3CB, IL1RAP, and OSMR coexisting in early-onset and full-term preeclampsia." (PMID 39148025, 2024). "PCR experiment results indicate an increase in the expression levels of CXCR6, PIK3CB, and OSMR at the RNA level in both subtypes of preeclampsia." (PMID 39148025, 2024). "This study identified four immune-related genes, namely CXCR6, PIK3CB, and OSMR, whose roles in the pathogenesis of preeclampsia have not been fully elucidated." (PMID 39148025, 2024).
rheumatoid arthritis (1 paper, 2023). A chronic, systemic autoimmune disorder characterized by inflammation in the synovial membranes and articular surfaces. "An earlier study revealed that in the context of type 1 inflammation, OSM enhances the expression of OSMR and IL-1R1 in synovial fibroblasts, thereby amplifying the pathological effects of both OSM and IL-1 in rheumatoid arthritis (RA)." (PMID 38137445, 2023).
scleroderma (1 paper, 2020). Scleroderma is a rare autoimmune connective tissue disorder characterized by abnormal hardening of the skin and, sometimes, other organs. "Blocking the OSM/OSMRβ pathway or inhibiting the STAT3 pathway could serve as a potential therapy for patients with scleroderma." (PMID 32736577, 2020).
skin inflammation (1 paper, 2017). "However, in AND Tg mice lacking both DOCK8 and OSMR (Dock8−/−Osmr−/− AND Tg), scratching bouts per 2 h were reduced to 11.5±9.3, as compared with 200.8±135.8 in Dock8−/−Osmr+/− AND Tg mice, and they did not develop skin inflammation." (PMID 28067314, 2017).
synovial sarcoma (1 paper, 2022). "Here, we detail the overexpression of OSMR in synovial sarcoma and highlight its potential as a target for therapy." (PMID 35745569, 2022). "Also, OSMR is upregulated in mouse models for synovial sarcoma as demonstrated by western blot and immunohistochemistry, and the protein is present in both primary and metastatic sites of disease." (PMID 35745569, 2022). "In this study, we develop an RIT therapy that targets OSMR and shows that the OSMR protein is present in substantial quantities in a subset of synovial sarcoma and that OSMR expression is independent of the metastatic state." (PMID 35745569, 2022). "Another benefit to this model of therapy is that it is not specific to synovial sarcoma, but rather it is indicated for any malignancy which exhibits an overexpression of OSMR." (PMID 35745569, 2022).
systemic sclerosis (1 paper, 2023). A chronic disorder, possibly autoimmune, marked by excessive production of collagen which results in hardening and thickening of body tissues. "An electrochemical immunosensor for autoantibodies against oncostatin-M receptor (OSMR), which has been associated with the AD known as systemic sclerosis, was developed." (PMID 37571553, 2023).
thyroid cancer (1 paper, 2022). "Our finding on the OSMR variant, rs2278329 (c.1657G>A: p.D553N), which predominately affects CRC and UC, is analogous to prior studies on OSMR that looked at the role of OSMR in inflammation and its potential link with other cancers such as bladder and thyroid cancer." (PMID 36232773, 2022).
viral infections (1 paper, 2024). "Our analysis specifically indicates the involvement of CXCR6, PIK3CB, and OSMR in the regulation of the RIG-I-like receptor signaling pathway, a common immune signaling pathway crucial for innate immunity, inflammation, and the upregulation of antiviral proteins to control viral infections." (PMID 39148025, 2024).
tumor (62 papers, 2008 to 2026). "The results showed that OSMR deficiency significantly increased the levels of the anti‐tumor immune cytokines IFN‐γ and TNF‐α." (PMID 39815665, 2025). "Our results provide further support to the importance of this axis in metastatic ccRCC, as OSM expression was expressed in the Macro-1 and Macro-3 populations, while the expression of OSMR was found in tumor-associated MSC-2 cells." (PMID 38281962, 2024). "Given the more significant reduction in tumor growth and improved survival rates in C57 mice with OSMR‐deficient GBM compared to NSC mice, we hypothesized that OSMR may influence the anti‐tumor function of the immune system." (PMID 39815665, 2025). "Our results support the relationship of the OSM-OSMR axis in promoting an osteolytic microenvironment as the tumor-associated MSC-2 population as well as the tumor cells themselves gain expression of OSMR, thereby favoring aberrant osteoclast formation and differentiation." (PMID 38281962, 2024). "We examined whether OSM exerts a direct pro-tumoral activity on cancer cells or has an indirect effect through the activation of cells present in the peritumoral environment by assessing tumor growth in mice deficient for the OSMRβ subunit (OSMR-KO) and their WT littermates." (PMID 30559930, 2018). "Oncostatin M (OSM), an IL-6 family cytokine primarily secreted by immune cells, has been shown to activate the STAT3 pathway in tumor cells via the OSM receptor (OSMR), thereby promoting tumor proliferation and metastasis." (PMID 41383622, 2025). "The poorer prognosis of tumors with high OSMR transcripts is consistent with previously reported effects of OSM or OSMR gene knock-down on these tumor types." (PMID 41040517, 2025). "The results indicated that in GBM tumor tissue, OSMR and FMOD were primarily distributed in astrocytes, IGFBP6 in NPC, G0S2 in macrophages, and IGHG2 in T cells." (PMID 39815665, 2025). "In contrast to LIFR, OSMR is highly expressed in fibroblasts, endothelial cells, and predominantly expressed in tumor cells compared to normal epithelial cells." (PMID 38839865, 2024). "OSM plays a crucial role in TAM-tumor interactions by binding to its receptor, OSMR, on tumor and stromal cells, activating various signaling pathways, including Jak-STAT." (PMID 39286635, 2024). "We also identified genes encoding membrane receptors (IL7R, OSMR, EGFR) and transcriptional regulators (BNC2, BNC1, HMGA2, KLF7, NR3C1) as enriched in Basal tumours." (PMID 36944729, 2023). "Treatment with OSM increased GC tumor size and incidence of peritoneal dissemination in vivo with attenuation being reached through OSMRβ inhibition." (PMID 37841259, 2023). "Immunohistochemistry staining for OSMR protein was also performed in both primary tumor samples and lung metastatic samples." (PMID 35745569, 2022). "As a tumor suppressor receptor, OSMR can inhibit the growth of tumor cells and induce their differentiation in various ways; this is a cytokine with good application prospects." (PMID 36142828, 2022). "The Oncostatin-M receptor (OSMR) is widely distributed on the surface of many tumor cells, endothelial cells, and epithelial cells." (PMID 35717380, 2022). "We also found that tumor progression-related genes were expressed specifically in a subpopulation of tumor cells with a high expression of OSMR." (PMID 36551576, 2022). "The OSMR expression profile has been found to be somewhat unpredictable and unrelated to metastatic status or tumor phenotype, making it difficult to predict which patients would be good candidates for an anti-OSMR RIT." (PMID 35745569, 2022). "Depletion of OSMR in the TME resulted in delayed tumor onset and tumor growth, confirming that stromal OSMR signaling contributes to cancer progression." (PMID 35192545, 2022).
tumor (continued). "Measurement of RNA levels and expression as well as protein expression in multiple tumor types has revealed that OSMR is overexpressed in some synovial sarcoma tumors and that the expression level is abundant enough for targeted therapy." (PMID 35745569, 2022). "Consistent with the scRNA-seq data, OSMR was broadly expressed within the VIMpos tumour stroma, however, OSMR-positive cells were also observed within the epithelium (PanCKpos) cells." (PMID 34921158, 2021). "ANXA2 promotes tumor proliferation by upregulating several oncogenes, such as β-catenin, cyclin D1, oncostatin M receptor (OSMR), and c-Myc26–29." (PMID 33712571, 2021). "Analysis of normal tissue samples (GTEx) and human PDA tumours (TCGA PanCancer PAAD) revealed a significantly higher expression level of OSMR and its cognate ligand, OSM, in human PDA compared to normal pancreatic tissue." (PMID 34921158, 2021). "OSMR can regulate cell apoptosis and proliferation, thereby affecting tumor cells and promoting tumor development." (PMID 34422217, 2021). "Here, we describe how heterocellular Oncostatin M (OSM) - Oncostatin M Receptor (OSMR) signalling reprograms fibroblasts, regulates tumour growth and metastasis." (PMID 34921158, 2021). "Oncostatin M receptor (OSMR) is widely distributed on the surface of many tumor cells, endothelial cells and epithelial cells." (PMID 34630121, 2021). "To assess OSM signaling, which occurs by OSM binding to the OSMR complex on tumor cells, we investigated the expression of the beta subunit of OSMR." (PMID 34011405, 2021). "Mice bearing ANXA2-overexpressing GBM exhibited shorter survival times compared with control tumor-bearing mice, whereas OSMR knockdown increased the survival time and diminished ANXA2-mediated tumor invasion, angiogenesis, and growth." (PMID 32248843, 2020). "These all reveal that OSMR plays a role in tumor metabolism and possibly affects the chances of survival." (PMID 30755233, 2019). "Studies showed that OSMR is expressed by multiple neoplastic cells and tumor tissues, but the exact OSM–OSMR mechanisms seem to be influenced by cell-type and tumor types." (PMID 30755233, 2019). "It should be noted that the majority of tumor cells express the Oncostatin M Receptor, as indicated by the online human protein atlas." (PMID 28147314, 2017). "At the same time, cancer cells from more aggressive tumor types express markedly higher levels of OSM Receptor (OSMR)." (PMID 26742077, 2016). "Our accumulated data 5,18,46 suggest that analogous benefits will also be obtained in cervical SCC (and potentially other SCCs where OSMR is overexpressed) by reducing tumour cell migration and invasion and inhibiting angiogenesis." (PMID 24659184, 2014). "Some tumours, including lung adenocarcinomas and oesophageal SCCs, seem to express a truncated and soluble form of OSMR, which possibly operates as a decoy receptor for OSM 40–42." (PMID 24659184, 2014). "Our accumulated data ( 4,6 and the present study) suggest that analogous benefits will also be obtained in cervical SCC (and potentially other tumour types where OSMR is over-expressed), by reducing tumour cell migration and invasion." (PMID 23765377, 2013). "OSMR expression was noted in all 8 canine tumor samples evaluated as well as the normal canine osteoblasts while OSM expression was detected in all samples although 2 of these were weak; normal canine osteoblasts did not express OSM." (PMID 21481226, 2011). "The expression of B4GALT1 and OSMR in tumor was three and four times lower than in normal tissue (NN), respectively (right)." (PMID 19662090, 2009). "Upon ligand binding, OSMR can activate signaling pathways implicated in cancer such as STAT, PI3/AKT, and mediates inhibition of tumor growth." (PMID 18559093, 2008).